APC (APC regulator of Wnt signaling pathway)
Diseases named in the same sentence as APC in open-access papers (continued):
Sharing a sentence is not in itself a finding about the gene and the disease.
colorectal cancer (continued). "Mutation of the APC gene is a common early event in colorectal cancer, however lower rates have been reported in younger cohorts of colorectal cancer patients." (PMID 33352971, 2020). "Colorectal cancers exhibit evidence of Wnt signaling pathway activation associated with loss of function of the tumor regulator APC." (PMID 33665169, 2020). "Within the sample subgroups, colorectal cancer was significantly enriched for APC mutations (40/54 colorectal cancer samples), ZFHX3 (13/54 samples) and FBXW7 (13/54)." (PMID 32306292, 2020). "Activation of the Wnt signalling pathway, predominantly through mutations in the APC gene, is a key oncogenic driver in most colorectal cancers." (PMID 32640573, 2020). "Apart from the most frequent mutations of APC in colorectal cancer and CTNNB1 in hepatocellular carcinoma, deregulations of several extracellular modulators of WNT-signaling e.g., DKKs, sFRPs and WIF1 also contribute to cancer development." (PMID 32659938, 2020). "‘Annurca’ and Malus domestica cv ‘Limoncella’, decreased Wnt signaling in cells carrying APC mutations upregulating the cascade and in ex vivo biopsies of patients with colorectal cancer cells carrying APC mutations." (PMID 32131438, 2020). "BRAF mutant colorectal cancers with truncating APC mutation tended to arise earlier in life, and presented at a significantly later stage." (PMID 32384699, 2020). "Although the most frequent mutations in colorectal cancer (CRC) involve adenomatous polyposis coli (APC) gene and dysregulation of β-catenin signaling, the Hippo pathway has been found to contribute to CRC tumorigenesis." (PMID 33271948, 2020). "APC mutation and promoter hypermethylation are two important mechanisms in carcinogenesis and colorectal cancer (CRC) progression." (PMID 33127962, 2020). "Mutations in the APC gene play a rate-limiting role in majority of sporadic colorectal cancers and hypermethylation of its promoter is closely related to cancer development." (PMID 32458646, 2020). "Somatic EGFR mutations were frequent in lung cancers, whereas somatic KRAS and APC mutations were frequent in colorectal cancers." (PMID 33193564, 2020). "APC was the most common mutational gene in colorectal cancer, and its mutation has indicated a highly significant association with immune resistance." (PMID 33013820, 2020). "The initial point is the APC suppressor gene mutation, found in many patients suffering from colorectal cancer, including patients with the hereditary familial adenomatous polyposis (FAP) disorder." (PMID 32403316, 2020). "For example, somatic mutations in the adenomatous polyposis coli (APC) gene, an essential factor for balancing Wnt activity, are found in approximately 80% of all colorectal carcinomas." (PMID 33352769, 2020). "Further, the APC gene mutation is a well-defined and known cause of familial adenomatous polyposis, and afflicted individuals are at significant risk of developing colorectal carcinoma." (PMID 32066498, 2020). "There have been abundant research results on the abnormal activation of Wnt/β-catenin pathway, mostly by inactivating mutations of APC, in various human cancers, most notably colorectal carcinomas (CRCs)." (PMID 33153498, 2020). "Downregulation of APC resulted in the accumulation of beta-catenin in the nucleus and increased transcription of the downstream genes associated with the development of colorectal carcinoma." (PMID 33092235, 2020).
colorectal cancer (continued). "The high rate of somatic APC mutations in sporadic colorectal cancer is consistent with inactivation of the APC protein playing a critical role in the initiation of colorectal cancers." (PMID 31258845, 2019). "In the majority of colorectal cancer cases this is due to reduced destruction complex activity after mutations of APC." (PMID 31534175, 2019). "The APC sequence is a well-known mutational hotspot in APC-mutated colorectal cancer and is also a hotspot for mutation during DNA synthesis by K289M pol β." (PMID 31732732, 2019). "Niclosamide has been shown to elicit anticancer activity against adenomatous polyposis coli (APC)-mutated colorectal cancer through downregulating the Wnt signaling pathway." (PMID 31581665, 2019). "We previously demonstrated that K289M induces mutations specifically within the AACAA sequence context that is present at 22 sites within the adenomatous polyposis coli (APC) gene, and which is mutated in 80% of familial colorectal cancers." (PMID 31732732, 2019). "For example, the pathway is frequently activated in colorectal cancer (CRC) as a result of the mutation of adenomatous polyposis coli (APC)." (PMID 34691990, 2019). "APC gene mutation is a gate keeper event for colorectal cancer development that activates canonical Wnt signaling." (PMID 30496442, 2019). "Recently, we have identified DKK2 as a novel tumor immune-suppressive protein in the microenvironment in colorectal cancer carrying APC mutation." (PMID 31372243, 2019). "Frequent APC mutations in colorectal cancer: The APC protein is an important component of the destruction complex in canonical WNT signaling." (PMID 31382613, 2019). "Oncogenic APC mutations have been well characterized in colorectal carcinoma because they are dominant mutations that drive the development of colorectal cancer." (PMID 31372243, 2019). "The most frequently mutated gene in colorectal cancer is APC (adenomatous polyposis coli) that is a β-catenin destruction complex component." (PMID 31817828, 2019). "In colorectal cancer, APC loss-of-function mutations synergize with KRAS-activating mutations to activate cancer stem cells." (PMID 31213486, 2019). "About 90% of colorectal cancers (CRCs) are induced by loss-of-function mutations in the adenomatous polyposis coli (APC) tumor suppressor gene, followed by nuclear accumulation of the canonical WNT signaling effector β-catenin." (PMID 30717152, 2019). "WNT signaling activation in colorectal cancers (CRCs) occurs through APC inactivation or β-catenin mutations." (PMID 31804558, 2019). "Consistent with this idea, APC mutations, which are present in approximately ~80% of colorectal cancers, are indeed mostly loss of function and/or truncating mutations." (PMID 31382613, 2019). "The majority of colorectal cancers are induced by subsequent mutations in APC and KRAS genes leading to aberrant activation of both canonical WNT and RAS signaling." (PMID 30717152, 2019).
colorectal cancer (continued). "Our recent studies also showed that DKK2 promotes tumor progression by suppressing cytotoxic immune cell activation in colorectal carcinoma with APC mutations." (PMID 31372243, 2019). "The adenomatous polyposis coli (APC) gene is mutated within specific sequence contexts in colorectal carcinomas but the underlying mechanism is not fully understood." (PMID 31732732, 2019). "Our previous study has proved that anti-DKK2 antibody 5F8 suppressed the growth of colorectal carcinoma with APC mutations, illustrating a new target agent of APC-mutated tumors." (PMID 31372243, 2019). "Inactivating APC mutations in colorectal carcinoma has been well characterized, leading to the approaches targeting on dysregulated APC pathway." (PMID 31372243, 2019). "The authors underline a need to identify patients earlier with germline adenomatous polyposis coli (APC) mutations for early colorectal carcinoma screening." (PMID 31718024, 2019). "In our recent study, we uncovered a function of DKK2 in promoting tumor progression by suppressing cytotoxic immune cell activation in colorectal carcinoma with APC mutations." (PMID 31372243, 2019). "The detailed molecular mechanism by which APC mutations predispose to the development of colorectal cancer is not completely understood." (PMID 30024920, 2018). "Such a phenomenon has previously been observed for a polymorphism that is associated with a hypermutability of the APC gene involved in colorectal cancer." (PMID 29159601, 2018). "APC mutation has traditionally been regarded as the initiating event in sporadic colorectal cancers that develop along the canonical pathway 19, and PTEN mutation is thought to play a similar role in sporadic endometrioid endometrial cancers." (PMID 29604063, 2018). "For example, a report suggests APC mutations can correlate with high expression levels of β-catenin whereas wild-type APC expression can reduce β-catenin levels in colorectal cancer cells." (PMID 29435196, 2018). "The importance of Wnt signaling in gut homeostasis is highlighted by the recurring mutations of the adenomatous polyposis coli (APC) gene, encoding a negative regulator of Wnt signaling, in human colorectal cancers (CRCs)." (PMID 29346117, 2018). "As a model system we used two unrelated colorectal cancer cell lines with truncating APC mutations (SW480, DLD1) and one with a stabilizing β-catenin mutation (HCT116)." (PMID 30338040, 2018). "The loss of function in APC can result in the activation of Wnt signaling in colorectal cancer and hepatocellular carcinoma." (PMID 30619485, 2018). "Analysis of high‐confidence pathogenic APC mutations in colorectal cancers revealed similar results [corresponding proportions nine of 14 (64.3%) versus 10 of 69 (14.5%) mutations; p = 0.012, Fisher's exact test]." (PMID 29604063, 2018). "This approach promises novel treatment opportunities for FAP patients with somatic APC gene mutations to delay and/or treat colorectal cancer." (PMID 30256815, 2018). "Germline mutations of the tumor suppressor gene adenomatous polyposis coli (APC) are associated with the familial cancer syndrome adenomatous polyposis coli, which predisposes its carriers to early onset colorectal cancer." (PMID 29649096, 2018).
colorectal cancer (continued). "A classic example of dysregulated Wnt signaling is colorectal cancer wherein the loss of Adenomatous Polyposis Coli (APC), a negative regulator of Wnt signaling triggers tumorigenesis." (PMID 29448933, 2018). "Mutations affecting other components of the Wnt pathway substitute for APC mutations in most other colorectal cancer cases." (PMID 29615557, 2018). "We have previously shown that in colorectal cancer Rapamycin-induced reduction of elongation suppresses intestinal regeneration and tumourigenesis following APC loss." (PMID 30405205, 2018). "Similar findings were reported for colorectal cancer by The Cancer Genome Atlas, where tumors harboring APC mutations were also found to harbor other WNT pathway alterations." (PMID 30224629, 2018). "These defects resemble mammalian intestinal adenomas that arise following loss of APC, highlighting the potential of using the Drosophila Apc1 mutant as a model to study colorectal cancers." (PMID 29615557, 2018). "Wnt signaling has been widely implicated in cancer, especially colorectal cancer, in which mutation of key regulatory factors of the Wnt pathway (mainly APC and CTNNB1), was found in ninety percent of tumors, resulting in activation of the Wnt pathway." (PMID 29515771, 2018). "This latter pathway involves the previously well-defined series of genetic aberrations such as APC mutation and chromosomal instability and accounts for the majority of colorectal cancer." (PMID 30598662, 2018). "For the dataset of all mutations, the cancer type-specific six gene mutation biomarkers were APC for colorectal cancer, PTEN for endometrial cancer, BRAF for thyroid cancer and MUC16, DNAH5, TTN for cutaneous melanoma." (PMID 30662873, 2018). "Mutations in the gene Adenomatous Polyposis Coli or APC appear in most sporadic cases of colorectal cancer and it is the most frequent mutation causing hereditary Familial Adenomatous Polyposis." (PMID 30024920, 2018). "In contrast, the mutation of the APC gene in sporadic colorectal cancers occurs at the level of an APC gene region—codons 1281–1256, forming the so-called mutation cluster region (MCR)—involved in β-catenin downregulation." (PMID 29652830, 2018). "Third, genome sequencing data not only confirmed that in human colorectal cancers, multiple mutations are acquired in addition to APC, but also revealed that these mutations exist in distinct combinations in different tumors." (PMID 29615557, 2018). "Chromatin immunoprecipitation of APC and next-generation sequencing were performed from HCT-116 colon cancer cells, which express wild-type APC yet can model the APC loss observed in the majority of colorectal cancers following transient siRNA-based silencing." (PMID 30131849, 2018). "In this respect, a common mutation in colorectal cancers involves the tumor suppressor adenomatous polyposis coli (APC) gene." (PMID 29682205, 2018). "The Wnt signalling pathway is commonly activated in conventional colorectal cancer via truncating APC mutations." (PMID 30598662, 2018). "Recently, Christie and coworkers analyzed the entire spectrum of mutated events involving the APC gene in a large population (624 patients) of colorectal cancer patients." (PMID 29652830, 2018). "Among the MMR-proficient tumors, at least 8% had a germline in at least one gene (in some cases, mutations in high-penetrance colorectal cancer genes, such as APC, PMS2, MUTYH, SMAD4)." (PMID 29652830, 2018). "Deregulation of the Wnt pathway, often due to loss of the negative regulator APC, is found in ~80% of colorectal cancer (CRC)." (PMID 30559928, 2018).
colorectal cancer (continued). "Over 90% of colorectal carcinomas have alterations in Wnt signaling; mutations in the adenomatous polyposis coli (APC) tumor suppressor or activating mutations in β-catenin account for ~80% of cases." (PMID 29495399, 2018). "Inactivation of APC is an important factor that predisposes towards colorectal cancer and is associated with enhanced mTORC1 signalling." (PMID 29186827, 2017). "The first modified phenotype is an APC mutant, commonly implicated in colorectal cancer, in which the function of the β-catenin destruction complex is either partially or wholly impaired and therefore has a reduced binding affinity for β-catenin." (PMID 28245235, 2017). "Genetic changes such as activated oncogenes or altered tumour suppressor genes (such as APC) in tumour cells are responsible for many aspects of neoplasia, indeed, over 80% of colorectal cancer cases are proposed to be due to the loss of APC." (PMID 28650985, 2017). "Familial adenomatous polyposis (FAP) is an autosomal-dominantly inherited form of colorectal cancer (CRC) caused by mutation in the adenomatous polyposis coli (APC) gene." (PMID 28306719, 2017). "Less frequently, loss-of-function mutation of AXIN1, AXIN2, or APC is found in 3.2%, 0.4%, and 0.2% of HCCs respectively, evidently contrasting with the situation in colorectal cancer, where up to 80% of cancers display mutated APC." (PMID 28035485, 2017). "According to Boman and Fields mutations in the APC gene, found in most colorectal cancers, would cause abnormal crypt production, disorientation of the crypts, and increased crypt production leading to colorectal adenomas." (PMID 28273142, 2017). "The activation of aberrant Wnt/β-catenin signalling is a critical early step in the majority of colorectal cancers with most tumours harbouring APC or β -catenin mutations; leading to enrichment of colorectal cancer stem cells." (PMID 28641310, 2017). "Mutations in the APC gene are associated with a specific form of inherited predisposition to colorectal cancer." (PMID 28502252, 2017). "Overexpression of the Wnt pathway by either inactivation of the adenomatous polyposis coli (APC) gene or activating mutations in β‐catenin (CTNNB1) has been observed in most of the colorectal cancers (CRCs) following the classical adenoma–carcinoma sequence." (PMID 28159860, 2017). "In this study, we found that the APC gene SNP rs11954856 was associated with colorectal cancer and increased the expression levels of genes in the Wnt/β-catenin signaling pathway in the CRC patients." (PMID 29050326, 2017). "In colorectal cancer, mutation in adenomatous polyposis coli (APC) tumor suppressor gene was associated with the aberrant stabilization of β-catenin and upregulation of survivin." (PMID 28536639, 2017). "The Wnt/β-catenin signaling pathway is of importance for the development of colorectal cancer with more than 80% mutation in APC (adenomatous polyposis coli) and about 5% activating mutations in β-catenin." (PMID 28153010, 2017). "Fzd7 can activate Wnt/β-catenin signaling in colorectal cancer cells despite the presence of APC or CTNNB1 mutations." (PMID 29207657, 2017). "According to the LOVD database for Chinese colorectal cancer patients, in Chinese population, 60% of the previously reported APC gene mutations causes FAP, are missense mutations." (PMID 28423518, 2017). "About 80% patients with sporadic colorectal cancers carry APC mutation, while half of colon cancer patients with wild-type APC carry mutations in β-catenin." (PMID 29225578, 2017). "A greater frequency of variants in genes encoding DNA mismatch repair functions and APC likely plays major roles in colorectal cancer initiation and higher incidence of the disease in African Americans." (PMID 29245953, 2017). "Mutations in APC and β-catenin are among the earlier events that lead to hyperplasia in the intestinal crypts leading to colorectal cancer development." (PMID 28153010, 2017).